INS (insulin)
Diseases named in the same sentence as INS in open-access papers (continued):
Sharing a sentence is not in itself a finding about the gene and the disease.
Insulin resistance (continued). "Accordingly, mice lacking Nfil3, which is critical for NK cell differentiation, or genetic loss of NCR1 or IFNγ resulted in improved insulin sensitivity, while treating mice with IL-15 to expand NK cells led to insulin resistance." (PMID 34837070, 2022). "Although GH has antagonistic effects on insulin action, its deficiency leads to insulin resistance and glucose intolerance, probably due to specific changes in fat distribution, such as increased visceral adipose tissue and ectopic fat accumulation." (PMID 35448486, 2022). "In fact, insulin resistance that reflects the progressive loss of the action of insulin on target tissues is also an independent risk factor for developing systemic inflammation that often accompanies atherosclerotic cardiovascular disease." (PMID 36286282, 2022). "Insulin resistance and associated reductions in cardiac insulin metabolic signaling are major factors for the development of heart failure." (PMID 35328064, 2022). "Based on the evidence, loss of dynamic physiologic insulin signaling plays a major role in the pathophysiology of insulin resistance (IR)." (PMID 35163806, 2022). "Insulin resistance is associated with reduced responses to insulin signaling in the IR/IRS-1/PI3K signaling pathway." (PMID 35563135, 2022). "T2D is caused by insulin resistance and is defined as the inability of insulin to increase glucose uptake and utilization." (PMID 36339572, 2022). "Chronic exposure to insulin caused mouse macrophages to develop insulin resistance characterized by increased glycolysis and a unique M2-like phenotype, which explains changes in macrophage response and a trained immune status associated with PCOS." (PMID 36118901, 2022). "There was a strong positive significant association between insulin resistance and insulin levels in participants (r = 0.960, p < 0.001)." (PMID 35736651, 2022). "Previously, it was thought that insulin resistance causes an increase in plasma glucose levels, which contribute to the need for pancreatic insulin-secreting cells (β-cells) to produce and secrete more insulin." (PMID 36419920, 2022). "This interaction between genetic predisposition and insulin-resistant factors results in an irreversible loss of pancreatic b-cell function, along with a state of insulin resistance." (PMID 35993079, 2022). "rs56146133 also has nominal associations with fasting insulin, glucose, and insulin resistance index (5 × 10–5 < P < 0.05)." (PMID 36505257, 2022). "Supporting this notion, patients with type II diabetes, who have insulin resistance and thus higher levels of circulating insulin, are at higher risk for various types of cancers due to the mitogenic effects of insulin." (PMID 35804992, 2022). "Insulin resistance in skeletal muscle is manifested by a decrease in insulin-stimulated glucose uptake, associated with impaired insulin signaling, glucose transport, oxidative phosphorylation, and glycogen synthesis." (PMID 36230963, 2022). "These include biological factors, such as predisposition to insulin resistance, augmented insulin secretion and abdominal obesity, as well as complex socioeconomic and cultural factors." (PMID 35858014, 2022). "Insulin resistance is an impaired cellular, tissue and whole‐body response to insulin and is one of the main underlying pathophysiological mechanisms leading to type‐2 diabetes (T2D)." (PMID 35964329, 2022). "Associations between insulin resistance/endothelial dysfunction and insulin sensitivity/basal endothelial NO production have been reported in patients with metabolic and cardiovascular disorders." (PMID 36550568, 2022). "This excess and/or underutilization of endogenous antioxidants can cause oxidative stress, causing β-cell dysfunction and insulin resistance by disrupting insulin signaling with its receptor to activate absorption of glucose." (PMID 36145129, 2022).
Insulin resistance (continued). "It has been proposed that insulin resistance causes a compensatory decrease in the ICR that increases the plasma insulin concentration and that this compensatory response is impaired in individuals with T2D." (PMID 34905513, 2022). "In our work, we found that administration of SA to HFD/STZ-induced T2DM mice significantly inhibited weight loss and the FBG level while increasing insulin sensitivity and improving insulin resistance." (PMID 36618687, 2022). "Previous studies have shown that hypoxemia is associated with decreased insulin sensitivity and varying degrees of insulin resistance." (PMID 35698229, 2022). "All of these can be linked to a hindrance in insulin signaling pathways, leading to insulin resistance." (PMID 35164215, 2022). "Regarding proline concentrations, several authors indicate that a high proline profile is associated with obesity, insulin resistance, hypertriglyceridemia, and decreased glucose-stimulated insulin secretion." (PMID 36145054, 2022). "A marked reduction of growth promoting GH/IGF-1 and insulin characterized early postnatal life and a decrease in testosterone activity at puberty coupled with insulin-resistance lead to a male-specific deficiency by adulthood." (PMID 35025875, 2022). "The CAFR diet in females decreased BW, Lee index, and adiposity and improved metabolic risk factors (decreased serum glucose, insulin, triacylglycerides, and insulin resistance), while CAFR in males decreased only adiposity and leptin levels." (PMID 36615803, 2022). "A strong positive correlation between the Hb levels and BMI was found, as well as positive associations between the Hb levels and fasting glucose and insulin levels, as well as insulin resistance indexes (i.e., HOMA-IR), similar to the findings in mice." (PMID 36361221, 2022). "Our recent findings that RAGE-mediated adipose tissue inflammation and insulin signaling are potentially important mechanisms, contributes to the development of obesity-associated insulin resistance." (PMID 36348465, 2022). "After surgery, ghrelin levels increase due to GH normalization and improved insulin sensitivity, but leptin levels also increase, which is associated with the development of insulin resistance." (PMID 35355553, 2022). "Obesity and sedentary lifestyle are states of insulin resistance that, when associated with genetic factors, adversely affect the functioning of pancreatic β cells, which, in a compensatory way, increase insulin secretion." (PMID 34821614, 2021). "Another study utilizing hepatocyte-specific IKKβ deficient mice found improved hepatic insulin response while maintaining systemic insulin resistance during obesity." (PMID 34957242, 2021). "Many studies have demonstrated that reduced insulin levels or insulin resistance are associated with protein breakdown, whereas increased insulin levels promote protein synthesis." (PMID 33918767, 2021). "Insulin treatment (100 ng/mL) was incorporated into the study in order to implement a model for insulin resistance and associated hyperinsulinemia, conditions that are often observed in obese and diabetic patients." (PMID 33690729, 2021). "Insulin resistance is defined as the resistance of target tissues such as skeletal muscles, adipocytes, and liver to insulin stimulation and is most often implicated in developing type II diabetes mellitus." (PMID 34746831, 2021). "Type-1 DM is characterized by autoimmune-mediated pancreatic β-cell results in the deficiency of insulin, whereas type-2 DM is peripheral insulin resistance." (PMID 33996978, 2021). "In obese patients, increased TMAO levels are associated with elevated fasting blood glucose and insulin levels and increased insulin resistance as assessed by homeostatic model assessment for insulin resistance (HOMA-IR)." (PMID 34445033, 2021).
Insulin resistance (continued). "It is especially remarkable how both compounds are capable of reducing insulin resistance by lowering glycemia and plasma insulin concentrations as well as obesity-associated inflammatory markers such as IL-6 and TNF-α." (PMID 34444748, 2021). "The underlying mechanisms that give rise to insulin resistance converge on deficient insulin signalling that limits the activation of factors involved in energy metabolism." (PMID 35002743, 2021). "The increased GnRHR‐AAb and testosterone were associated with the induced insulin resistance and impaired insulin response to a glucose challenge." (PMID 33356018, 2021). "Relevant studies have shown that S100A16 can reduce the sensitivity of 3T3-L1 to insulin, overexpression of S100A16 can promote lipid synthesis of 3T3-L1 preadipocytes, inhibiting glucose uptake under insulin stimulation, and cause insulin resistance." (PMID 33912559, 2021). "The importance of zDHHC7 in the general context of insulin action was underscored by the observation that the knockout mice had increased fasting serum glucose levels and insulin tolerance tests highlighted underlying insulin resistance." (PMID 33784857, 2021). "Clinically, insulin resistance (IR) refers to a state in which a given concentration of insulin is associated with a suboptimal response." (PMID 34684300, 2021). "Obesity-induced insulin resistance, insulin demand and inflammation are possible underlying mechanisms." (PMID 33828529, 2021). "Enhanced insulin resistance and predominantly decreased insulin secretion are considered to be the underlying causes of PTDM." (PMID 33810367, 2021). "Insulin resistance is the failure of cell to normally respond to insulin to reduce blood glucose level and is the key pathogenic feature of MetS." (PMID 33898478, 2021). "The measurement factors in the pathogenesis of T2DM are insulin resistance, a deteriorated insulin secretory capacity, and a genetic background associated with excess energy intake and physical inactivity." (PMID 35392577, 2021). "The two hallmarks of the disease are insulin resistance in peripheral tissues, tightly associated with increased body mass index (BMI), and dysfunction of insulin-producing β-cells found in pancreatic islets." (PMID 33670429, 2021). "Accumulating evidence has established a causal role for inflammation in the development of insulin resistance in insulin-responsive tissues, including the liver." (PMID 34684470, 2021). "Oxidative stress contributes to cellular injury such as β-cell dysfunction, insulin resistance and impaired glucose tolerance, all of which contribute to the worsening of pancreatic islet β-cell function, causing a deficiency in insulin release." (PMID 33808180, 2021). "Type 2 diabetes mellitus (T2DM) is a metabolic syndrome, chiefly associated with chronic hyperglycemia as a result of insulin resistance and inadequate insulin secretion." (PMID 34960064, 2021). "Insulin resistance is also associated with lipid accumulation and is defined as a state in which cells fail to react to the effects of insulin on glucose production." (PMID 34943908, 2021). "The American Diabetes Association (ADA) states that T2D is due to a progressive loss of adequate β-cell insulin secretion, frequently on the background of insulin resistance, which manifests clinically as hyperglycemia." (PMID 34685869, 2021). "Metabolic insulin resistance is strongly associated with microvascular insulin resistance (typically measured by a diminished action of insulin to enhance perfusion) in a number of tissues." (PMID 34299190, 2021). "Obese adolescents are at higher risk of developing associated complications such as insulin resistance (IR) (loss of sensitivity to insulin in the peripheral tissues)." (PMID 33438144, 2021). "Obesity is a well-known risk factor for GDM and insulin treatment, due to increased insulin resistance." (PMID 33767671, 2021).
Insulin resistance (continued). "As far as we know, T2DM is a chronic metabolic disease caused by insulin resistance and insufficient insulin secretion compensation response." (PMID 34952622, 2021). "Abnormal glucose tolerance in pregnancy is mainly caused by increased insulin resistance due to placenta-derived factors such as lactogen and prolactin, obesity, and inhibition of insulin signaling." (PMID 33776619, 2021). "This peripheral insulin resistance causes pancreatic β-cells to secrete more insulin, in a process known as compensatory hyperinsulinemia." (PMID 33562475, 2021). "In the present study and in line with previous literature, SHBG was associated inversely with insulin resistance, insulin secretion, and AGM, independently of BMI." (PMID 34153097, 2021). "Type 2 diabetes is a worldwide prevalent disease that is due to a progressive loss of adequate β-cell insulin secretion, frequently against a background of insulin resistance." (PMID 34685869, 2021). "As a consequence of long-term insulin resistance, the reduction in the number of functional β cells leads to a deficiency in insulin secretion." (PMID 33916828, 2021). "High dietary acid load and chronic metabolic acidosis are also closely linked to the reduced affinity of the insulin to its receptor, increased risk of insulin resistance, and subsequently, hyperglycemia." (PMID 34511069, 2021). "Several reports on pathophysiological mechanisms underline that glucocorticoids can induce insulin resistance, leading to the inhibition of the insulin signaling pathway." (PMID 34880914, 2021). "Ectopic lipid accumulation will result in the remarkable increase in lipid metabolites such as ceramide and diacylglycerol, which are verified to impair insulin signaling pathway and cause insulin resistance." (PMID 34414181, 2021). "In particular, type 2 diabetes is associated with insulin resistance (insulin action defect), i.e., where cells respond poorly to insulin, affecting their glucose intake." (PMID 34930452, 2021). "Many drugs cause insulin resistance or impaired insulin secretion, leading to diabetes in individuals with risk factors." (PMID 34840987, 2021). "Higher prepubertal HCB concentrations were associated with greater ratios of insulin resistance, higher serum insulin, and the homeostatic model assessment of insulin resistance (HOMA-IR) levels." (PMID 34281107, 2021). "Both high level of fasting serum insulin and insulin resistance are associated with increased risk of thyroid carcinoma." (PMID 34550096, 2021). "Taken together, exercise improves insulin sensitivity and glucose disposal, which would be expected to greatly benefit patients with cancer-associated insulin resistance and mitigate the oncogenic condition of hyperinsulinemia." (PMID 33801684, 2021). "The insufficient insulin secretion is associated with the dysfunction or loss of β-cells and the development of insulin resistance, which refers to a decrease in insulin sensitivity of insulin-targeted tissues or cells." (PMID 35141228, 2021). "Collectively the data demonstrate that RAGE-mediated adipose tissue inflammation and insulin-signaling are potentially important mechanisms that contribute to the development of obesity-associated insulin resistance." (PMID 34686659, 2021). "In conclusion, the present study showed that the presence of OSA increased spontaneous lipolysis in T2DM patients, which was associated with the severity of OSA, as well as with Insulin resistance and impaired insulin secretion." (PMID 33574418, 2021). "Obesity induces insulin resistance which produces a compensatory increase in insulin secretion, and the increase in insulin availability has been implicated in increased sodium reabsorption in the proximal tubule and the ascending loop of Henle." (PMID 33928108, 2021).
Insulin resistance (continued). "Recently, a potential causative association between environmental hazards and insulin resistance, and the molecular mechanism underlying the disruption of the insulin signaling pathway have been reported." (PMID 35111696, 2021). "Subsequently, we showed that GPR21 overexpression in HEK293T cells was associated with impaired insulin signalling, thus indicating a direct involvement in the establishment of insulin resistance." (PMID 34639123, 2021). "In insulin resistance conditions, some alterations in the genes associated with insulin signaling have been found." (PMID 34769060, 2021). "Type 2 DM is a heterogeneous group of disorders that display relative insulin deficiency and is usually associated with obesity, insulin resistance, impaired insulin secretion, and increased hepatic glucose production." (PMID 34134670, 2021). "Risk factors for insulin therapy identified in our population are concordant in recognizing a poor metabolic profile that can be the substrate of maladaptation to the insulin resistance state physiologically induced by pregnancy." (PMID 33767671, 2021). "In humans, increased visceral adipose tissue is associated with insulin resistance, dyslipidemia, and type 2 diabetes, while subcutaneous adipose tissue is associated with preserved insulin sensitivity and mitigates risk of metabolic disorders." (PMID 33647469, 2021). "Meanwhile, CX3CR1 can bind to fractalkine (FKN; also known as CX3CL1) and modulate the secretion of insulin and atherosclerosis associated with insulin resistance." (PMID 34269146, 2021). "Ketonemia, in turn, causes insulin resistance in dairy cows consistent with studies linking high BCS to reduced peripheral insulin sensitivity in the lipomobilization state." (PMID 33670528, 2021). "Phosphorylation of IRS-1 at Ser307, a potential mechanism underlying insulin resistance, attenuates insulin signaling pathways." (PMID 33968046, 2021). "IRTKS-deficient mice exhibit insulin resistance, including hyperglycemia, hyperinsulinemia, glucose intolerance, decreased insulin sensitivity, and increased hepatic glucose production." (PMID 34931130, 2021). "Insulin resistance refers to the diminished response of peripheral tissues to insulin and is considered the major risk factor for type 2 diabetes." (PMID 33498604, 2021). "Insulin resistance can develop in subclinical hypothyroidism as a result of a reduced rate of insulin-stimulated glucose transfer caused by a translocation of the glucose transporter type 2 (GLUT 2) gene." (PMID 35106234, 2021). "Another study found a positive association between PFOA and PFOS and increased insulin concentration, higher beta-cell activity, and elevated insulin resistance; the results were only significant among overweight children." (PMID 34564296, 2021). "Hyperglycaemia itself causes insulin resistance and following increasing insulin to regain normoglycaemia, insulin requirements often fall, and this increases the risk of hypoglycaemia." (PMID 34368024, 2021). "It is believed that ER stress leads to abnormal cell signaling in response to insulin, causing insulin resistance, as seen in diabesity." (PMID 33995826, 2021). "Several studies have linked insulin resistance to a dysfunctional Akt2 where its secretion is less than 50% compared with non-insulin resistant conditions." (PMID 33953863, 2021). "As a marker of subclinical inflammation, leukocytes are directly associated with insulin resistance and inversely correlated with insulin secretion." (PMID 34880914, 2021). "In fact, impaired insulin signaling was observed in the development of HD, indicating that a decrease in insulin sensitivity, also known as insulin resistance, is linked to mHtt-associated impairments." (PMID 34445125, 2021). "These experiments clearly point towards impaired insulin action in tanycytes of obese mice, and further suggest an unexplored relevance of tanycyte insulin resistance in the manifestation of obesity-associated phenotypes." (PMID 34931084, 2021).